ARSB (arylsulfatase B)
Description:
Removes sulfate groups from chondroitin-4-sulfate (C4S) and regulates its degradation. Involved in the regulation of cell adhesion, cell migration and invasion in colonic epithelium. In the central nervous system, is a regulator of neurite outgrowth and neuronal plasticity, acting through the control of sulfate glycosaminoglycans and neurocan levels (By similarity).
Synonyms: ASB; G4S; MPS6
Tractability: Antibody: its Gene Ontology location is reachable by antibodies, with high confidence; UniProt places it where antibodies can reach, with medium confidence; UniProt predicts a signal peptide or a membrane-spanning region. PROTAC: its protein half-life has been measured.
Target class: Enzyme; Hydrolase
Gene: Protein-coding gene on chromosome 5 (78,777,209 to 78,986,087, reverse strand). Ensembl gene ENSG00000113273.
Subcellular location: Lysosome; Cell surface
Subcellular location (Human Protein Atlas): Golgi apparatus
Pathways (Reactome):
Metabolism: CS/DS degradation; Glycosphingolipid catabolism
Disease: MPS VI - Maroteaux-Lamy syndrome
Immune System: Neutrophil degranulation
Metabolism of proteins: The activation of arylsulfatases
Gene Ontology:
Molecular function: N-acetylgalactosamine-4-sulfatase activity; arylsulfatase activity; sulfuric ester hydrolase activity
Biological process: chondroitin sulfate proteoglycan catabolic process; colon epithelial cell migration; regulation of epithelial cell migration; lysosomal transport; lysosome organization; positive regulation of neuron projection development; autophagy; response to estrogen; response to methylmercury; response to nutrient; response to pH
Cellular component: extracellular exosome; azurophil granule lumen; cell surface; endoplasmic reticulum lumen; extracellular region; ficolin-1-rich granule lumen; lysosomal lumen; lysosome
Genetic constraint (gnomAD): Loss-of-function variants: 45 observed, 55.9 expected, observed/expected ratio (o/e) 0.81, 90% interval 0.63 to 1.03. The upper end of that interval is the gene's LOEUF score, 1.03, which puts it in group 4 of 6, group 1 being the genes least tolerant of losing a copy. Missense variants: 672 observed, 668.3 expected, observed/expected ratio (o/e) 1.01, 90% interval 0.94 to 1.07. Synonymous variants: 269 observed, 258.13 expected, observed/expected ratio (o/e) 1.04, 90% interval 0.94 to 1.15.
Gene-disease validity (ClinGen):
ClinGen rates the evidence that ARSB causes each of these diseases.
mucopolysaccharidosis type 6 (autosomal recessive): Definitive. Mucopolysaccharidosis type 6 (MPS 6) is a lysosomal storage disease with progressive multisystem involvement, associated with a deficiency of arylsulfatase B (ASB) leading to the accumulation of dermatan sulfate.
Homologues: Orthologues: chimpanzee ARSB (100% identical), macaque ARSB (97% identical), pig ARSB (91% identical), guinea pig ARSB (84% identical), mouse Arsb (78% identical), rat Arsb (77% identical), tropical clawed frog arsb (69% identical), zebrafish ARSB (49% identical), Drosophila melanogaster CG7402 (28% identical), Drosophila melanogaster CG32191 (27% identical), Drosophila melanogaster CG7408 (26% identical), Drosophila melanogaster CG18278 (15% identical), and 1 more. Paralogues in human: ARSI (51% identical), ARSJ (50% identical), ARSL (26% identical), STS (26% identical), ARSF (25% identical), GALNS (25% identical), ARSD (25% identical), ARSA (24% identical), ARSH (24% identical), ARSG (23% identical), SGSH (21% identical), IDS (20% identical), and 4 more.
Diseases named in the same sentence as ARSB in open-access papers:
ARSB is named in the same sentence as 65 diseases in open-access papers, as found by Europe PMC text mining. Sharing a sentence is not in itself a finding about the gene and the disease. The quoted sentences say what the papers report.
mucopolysaccharidosis type 6 (62 papers, 2009 to 2026). "Mutations in the lysosomal enzyme arylsulfatase B result in the genetic disorder mucopolysaccharidosis VI." (PMID 41970838, 2026). "The ARSB mutation, which causes protein defects is known to be the cause of lysosomal storage disease (known as mucopolysaccharidosis type VI)." (PMID 40534738, 2025). "MPS VI (Maroteaux-Lamy syndrome) is caused by pathogenic mutations in ARSB, resulting in deficiency of the enzyme arylsulfatase B (ARSB) and lysosomal deposition of dermatan sulfate and chondroitin-4-sulfate." (PMID 39020431, 2024). "Mucopolysaccharidosis type VI (Maroteaux-Lamy syndrome OMIM#253200) results from a deficiency of the enzyme arylsulfatase B (ARSB)." (PMID 38425718, 2024). "Recombinant human ARSB is used successfully in enzyme replacement therapy of congenital ARSB deficiency, Mucopolysaccharidosis VI, by the administration of a weekly dose of 1.0 mg/kg IV." (PMID 38892038, 2024). "Mucopolysaccharidosis type VI (Maroteaux-Lamy syndrome) is a progressive multi-systemic autosomal recessive disease resulting from a deficiency of arylsulfatase B (N-acetylgalactosamine-4-sulfatase)." (PMID 36968901, 2023). "ARSB has long been known to localize to lysosomes, and mutations in the ARSB gene cause mucopolysaccharidosis VI." (PMID 37892834, 2023). "MPS VI, also known as Maroteaux-Lamy syndrome, is caused by deficiencies in N-acetylgalactosamine-4-sulfatase resulting from pathogenic variants in the arylsulfatase B (ARSB) gene and results in the accumulation of 4-sulfated chondroitin and dermatan sulfates." (PMID 37454964, 2023). "A patient with a c.454C>T mutation in the ARSB gene, typical of type VI mucopolysaccharidosis, had osteoporosis and multiple fractures of peripheral bones." (PMID 35052464, 2022). "Mucopolysaccharidosis VI, or Maroteaux–Lamy disease, is an autosomal recessive disease characterized by deficiency of the enzyme arylsulfatase B in the lysosomal catabolism of glycosaminoglycans." (PMID 35078524, 2022). "ARSB is also the causal gene of human mucopolysaccharidosis type VI (Maroteaux–Lamy syndrome), which is related to facial deformities and short stature." (PMID 35350434, 2022). "Inherited mutations of ARSB are the cause of Mucopolysaccharidosis (MPS) VI (Maroteaux-Lamy-Syndrome; phenotype MIM number is 253200), which is characterized by the accumulation of dermatan sulfate and chondroitin 4-sulfate (C4S) throughout the body." (PMID 36361933, 2022). "MPSVI, also known as Maroteaux-Lamy Syndrome, is caused by mutations in ARSB, leading to a deficiency in Arylsulfatase B." (PMID 36172050, 2022). "Mucopolysaccharidosis type VI, also known as Maroteaux-Lamy syndrome, is an autosomal recessive lysosomal disorder, due to the deficiency of the enzyme arylsulfatase B that leads to the accumulation of dermatan sulfate in the tissues and its urinary excretion." (PMID 38464407, 2021). "Mucopolysaccharidosis type VI (MPS VI) is a rare lysosomal storage disease caused by deficient activity of arylsulfatase B (ARSB)." (PMID 33985463, 2021). "MPS VI (Maroteaux-Lamy syndrome) results from deficiency of N-acetylgalactosamine-4-sulfatase (ARSB; MIM 253,200), which causes accumulation of DS and C4S." (PMID 34051828, 2021). "Mutations in the ARSB gene lead to the accumulation of glycosaminoglycans and cause type VI mucopolysaccharidosis." (PMID 33195324, 2020). "Mucopolysaccharidosis VI (MPS VI) is a very rare autosomal recessive disorder caused by mutations in the ARSB gene." (PMID 31660881, 2019). "Mucopolysaccharidosis (MPS) VI or Maroteaux-Lamy syndrome (253200) is an autosomal recessive lysosomal storage disorder caused by deficiency in N-acetylgalactosamine-4-sulfatase (arylsulfatase B)." (PMID 31142378, 2019). "Mucopolysaccharidosis type VI (MPS VI) or Maroteaux-Lamy syndrome is produced by the deficiency of the enzyme arylsulfatase B, responsible for the hydrolysis of N-acetyl-D-galactosamine, chondroitin sulfate, and dermatan sulfate." (PMID 30335002, 2018).
mucopolysaccharidosis type 6 (continued). "Genetic mutations of these enzymes lead to the lysosomal storage disorders Mucopolysaccharidosis VI (Maroteaux-Lamy-Disease), in which there is genetic mutation of ARSB, or Mucopolysaccharidosis IVA (Morquio A), in which there is genetic mutation of GALNS." (PMID 29245974, 2017). "Maroteaux-Lamy syndrome (MPS VI) is caused by a deficiency of N-acetylgalactosamine-4-sulfatase (arylsulfatase B) leading to increased excretion of dermatan sulfate." (PMID 27512882, 2016). "Mucopolysaccharidosis VI (MPS VI) is an autosomal recessive progressive multiorgan disorder due to mutation in the gene encoding the enzyme Arylsulfatase B (ARSB)." (PMID 24107440, 2013). "Mucopolysaccharidosis VI (MPS VI or Maroteaux-Lamy syndrome) is a rare autosomal recessive genetic disease caused by deficiency of the enzyme N-acetylgalactosamine-4-sulfatase or arylsulfatase B (ARSB)." (PMID 21637564, 2010). "Mucopolysaccharidosis VI (MPS VI), also known as Maroteaux-Lamy syndrome, is caused by deficiency of the lysosomal enzyme N-acetylgalactosamine-4-sulfatase (arylsulfatase B, ARSB)." (PMID 19531206, 2009). "MPS VI, also known as Maroteaux-Lamy syndrome, is caused by complete or partial loss of activity of the enzyme N-acetyl-galactosamine-4-sulfatase (arylsulfatase B, ARSB), which is involved in the breakdown of two different GAGs: dermatan sulfate and chondroitin 4-sulfate." (PMID 35236367, 2022). "This problem is well-illustrated by Mucopolysaccharidosis Type VI also known as Maroteaux–Lamy syndrome, in which the breakdown of glycosaminoglycans is damaged due to the deficiency in the enzyme arylsulfatase B (ARSB) caused by homozygous or compound heterozygous mutation in the ARSB gene (5q14)." (PMID 36289474, 2022). "Defects in arylsulfatase B are the cause of mucopolysaccharidosis type 6 [MIM:253200]." (PMID 23815589, 2013). "Furthermore, it should be noted that other types of MPS, such as Type VI (Maroteaux-Lamy syndrome) caused by mutations in the ARSB gene, leading to deficiency of arylsulfatase B (ARSB; also known as N−acetylgalactosamine−4−sulfatase), has also been found to be associated with cancer development." (PMID 37601653, 2023). "Galsulfase, indicated for Maroteaux-Lamy syndrome (MPS VI), addresses the deficiency of arylsulfatase B; laronidase, used for Hurler, Hurler-Scheie, and Scheie syndromes (MPS I), replaces the enzyme alpha-L-iduronidase." (PMID 40510111, 2025). "The relationship between IGF2R and endosomal uptake provides an avenue for exogenous ARSB-initiated intracellular effects, as evident in the treatment of Mucopolysaccharidosis VI by replacement therapy with exogenous ARSB." (PMID 40562100, 2025). "Mucopolysaccharidosis type VI (MPS VI), or Maroteaux-Lamy syndrome, is a rare, autosomal recessive lysosomal storage disorder caused by a deficiency in the enzyme arylsulfatase B (ARSB)." (PMID 41348912, 2025). "Mucopolysaccharidosis VI (MPS VI) is a rare, autosomal recessive lysosomal storage disease caused by mutations in the arylsulfatase B gene (ARSB)." (PMID 41348912, 2025). "Mucopolysaccharidosis VI (MPS VI, Maroteaux–Lamy syndrome) is an additional autosomal recessive form of MPS linked to mutations in the ARSB gene, resulting in arylsulfatase B deficiency." (PMID 39940729, 2025). "The mutated gene for arylsulfatase B (ARSB) leads to the reduced function of the enzyme, causing a lysosomal storage disorder – MPS type VI, also known as Maroteaux-Lamy syndrome." (PMID 37441579, 2023). "Mucopolysaccharidosis type VI (MPS VI) is an autosomal recessive lysosomal disorder caused by a mutation in the ARSB gene, which encodes arylsulfatase B (ARSB), and is characterized by glycosaminoglycan accumulation." (PMID 36032399, 2022). "The enzyme N-acetylgalactosamine-4-sulfatase (Arylsulfatase B; ARSB) was originally identified as a lysosomal enzyme which was deficient in Mucopolysaccharidosis VI (MPS VI; Maroteaux-Lamy Syndrome)." (PMID 36361933, 2022).
mucopolysaccharidosis type 6 (continued). "Mucopolysaccharidosis type VI (MPS VI, Maroteaux-Lamy syndrome, MPS VI, OMIM 253200) is caused by deficient activity of N-acetylgalactosamine-4-sulphatase (4-sulphatase, arylsulphatase B, ARSB, EC 3.1.6.12)." (PMID 36064607, 2022). "We have reported a cellular model of type VI mucopolysaccharidosis (MPS) to investigate these processes at the molecular level using human pulmonary artery endothelial (HPAEC) cells with a silenced ARSB gene." (PMID 32664626, 2020). "In general, homozygous or compound heterozygous mutations in the ARSB gene, underlie MPS type VI or Maroteaux-Lamy syndrome." (PMID 31973102, 2020). "Mucopolysaccharidosis VI (MPS VI, also known as Maroteaux-Lamy syndrome; OMIM #253200) is due to pathogenic mutations in the arylsulfatase B (ARSB) gene located on chromosome 5." (PMID 30442162, 2018). "ARSB is clinically approved for replacement therapy in patients with mucopolysaccharidosis VI and therefore represents an attractive candidate for translation to the human CNS." (PMID 29762123, 2018). "Testing for mucopolysaccharidosis Type VI (MPS VI) in cats, specifically the genetic testing of the L476P (c.1427T>C) and the D520N (c.1558G>A) variants in arylsulfatase B (ARSB), has come under scrutiny." (PMID 27370326, 2016). "A similar situation has recently developed for the genetic testing of mucopolysaccharidosis Type VI (MPS VI), an arylsulfatase B (ARSB) variant in cat breeds." (PMID 27370326, 2016). "Mucopolysaccharidosis VI (MPS VI) is a lysosomal storage disease with progressive multisystem involvement, associated with a deficiency of arylsulfatase B leading to the accumulation of dermatan sulfate." (PMID 20385007, 2010). "In clinical studies, AAV8.TBG.hARSB therapy with two copies of 101 bp of the AMBP enhancer and the −474/+3 region of the TBG promoter maintained 38–67% of normal arylsulfatase B (ARSB) activity in patients with mucopolysaccharidosis type VI (MPS VI) during 45 months of follow-up." (PMID 41511298, 2025). "Mucopolysaccharidosis type VI [OMIM:253200], also known as Maroteaux–Lamy syndrome, is a progressive AR LSD with an estimated prevalence of 1/43,000–1,500,000, caused by mutations affecting the ARSB gene on chromosome 5q14.1." (PMID 37239976, 2023). "Mucopolysaccharidosis VI (MPS VI) is a hereditary lysosomal storage disease caused by the absence of the enzyme arylsulfatase B (ARSB)." (PMID 36213247, 2022). "Subsequently, deficiency of ARSB was detected in cultured fibroblasts of patients with the Maroteaux-Lamy Syndrome (MLS), and the relationship between inherited deficiency of ARSB and MLS, subsequently identified as Mucopolysaccharidosis (MPS) VI, was clarified in several studies in the 1970s." (PMID 36361933, 2022). "We have recently described the efficacy of AAV2/8-mediated liver gene transfer in animal models of mucopolysaccharidosis VI (MPS VI), an LSD characterized by glycosaminoglycan (GAG) storage in various tissues including liver due to arylsulfatase B (ARSB) deficiency." (PMID 22428010, 2012). "The Mucopolysaccharidosis type VI (MPS VI), also known as Maroteaux-Lamy syndrome (OMIM 253200) is an autosomal recessive lysosomal disorder, caused by the deficiency of the enzyme N-acetylgalactosamine 4-sulfatase (also known as arylsulfatase B) due to mutations of the ARSB gene." (PMID 32075597, 2020). "We identify one analog that does not inhibit recombinant arylsulfatase B but can stabilize it against thermal denaturation as a potential lead compound in the treatment of mucopolysaccharidosis VI." (PMID 41970838, 2026). "MPS VI (Maroteaux-Lamy syndrome) is an autosomal recessive disease caused bymutations in the arylsulfatase B (ARSB) gene,resulting in reduced or absent enzyme activity of arylsulfatase B (ARSB),responsible for the breakdown of dermatan sulphate." (PMID 31132295, 2019).
lysosomal storage disorder (29 papers, 2010 to 2025). "Mucopolysaccharidosis Type VI (MPS VI) is a lysosomal storage disorder associated with biallelic pathogenic variants in the ARSB gene." (PMID 40677925, 2025). "Mucopolysaccharidosis type VI (MPSVI), an autosomal recessive lysosomal storage disorder caused by pathogenic variants in ARSB gene." (PMID 39845185, 2024). "In the liver, we target the Alb locus in newborn, proliferating hepatocytes of a mouse model of the severe lysosomal storage disease MPS VI to achieve stable therapeutic levels of arylsulfatase B (ARSB), the lysosomal enzyme which is deficient in MPS VI." (PMID 35414130, 2022). "MPS type VI (MPS VI), also known as Maroteaux–Lamy syndrome (OMIM 253200), is a rare autosomal recessive lysosomal storage disorder caused by the deficiency of arylsulfatase B (ARSB)." (PMID 32759694, 2020). "This study explores mcopolysaccharidosis VI (MPS VI) or Maroteaux–Lamy syndrome (OMIM #253200) which is an autosomal recessive lysosomal storage disease caused by the deficiency of arylsulfatase B enzyme." (PMID 30669586, 2019). "We recently demonstrated that AAV8-mediated liver gene transfer is effective in animal models of mucopolysaccharidosis type VI (MPS VI), a rare lysosomal storage disease that is caused by arylsulfatase B (ARSB) deficiency." (PMID 28932756, 2017). "Four PD cases in our cohort were identified with a LoF variant in the ARSB gene, in which mutations have previously been linked with the recessive lysosomal storage disorder, MPS VI (also called Maroteaux-Lamy syndrome)." (PMID 28137300, 2017). "Mucopolysaccharidosis type VI (MPS VI; Maroteaux-Lamy syndrome; MIM ID #253200) is an autosomal recessive lysosomal storage disorder, caused by mutations in the gene encoding arylsulfatase B (ARSB; N-acetylgalactosamine 4-sulfatase)." (PMID 24107440, 2013). "ARSB gene variants have often been associated to the lysosomal storage disorder MPS VI." (PMID 35186827, 2021). "MPS VI is a rare progressive lysosomal storage disorder caused by the deficit of the ARSB enzyme." (PMID 30524696, 2018). "Mucopolysaccharidosis type VI (Maroteaux-Lamy syndrome; MPS VI) is an autosomal recessive lysosomal storage disorder in which deficiency of N-acetylgalactosamine 4-sulfatase (arylsulfatase B; ARSB) leads to the storage of glycosaminoglycans (GAGs) in connective tissue." (PMID 23557332, 2013). "Mucopolysaccharidosis VI (MPS VI) or Maroteaux-Lamy syndrome (MIM # 253200) is an autosomal recessive lysosomal storage disorder described in 1963 by Dr. Pierre Maroteaux and Dr. Maurice Lamy and determined by mutations in the arylsulfatase B (ARSB) gene located in chromosome 5 (5q13-5q14)." (PMID 20385007, 2010). "The glycosaminoglycan-degrading enzyme arylsulfatase B, a gene related to lysosomal storage disorders, was also downregulated in our study." (PMID 34659154, 2021). "The enzymatic defect of ARSB leads to progressive lysosomal storage disorder and accumulation of glycosaminoglycan (GAG) dermatan sulfate (DS), which causes harmful effects on various organs and tissues and short stature." (PMID 30524696, 2018). "Substrate accumulation and associated cellular stress has been reported to induce markers of impaired autophagy and mitochondrial dysfunction in ARSB deficient fibroblasts from MPSVI patients, as in other lysosomal disorders." (PMID 28137300, 2017). "Mucopolysaccharidosis type VI (MPS VI, Maroteaux-Lamy syndrome) is a lysosomal storage disease caused by functional absence of the enzyme N-acetylgalactosamine 4-sulfatase (arylsulfatase B or ASB; E.C. 3.1.6.12)." (PMID 22669363, 2013). "Mucopolysaccharidosis type VI (MPS VI) is a severe lysosomal storage disorder without central nervous system involvement caused by arylsulfatase B (ARSB) deficiency." (PMID 22971959, 2013). "As a therapeutic transgene we used ARSB, the lysosomal hydrolase defective in MPS VI, a rare lysosomal storage disease." (PMID 35414130, 2022).
lysosomal storage disorder (continued). "We next tested the therapeutic potential of HITI in the liver of a mouse model of MPS VI, a severe lysosomal storage disease, and show that newborn MPS VI mice treated with AAV-HITI have stable serum ARSB levels up to 12 months after treatment, as well as normalized liver ARSB activity." (PMID 35414130, 2022).